IL6 (interleukin 6)
Diseases named in the same sentence as IL6 in open-access papers (continued):
Sharing a sentence is not in itself a finding about the gene and the disease.
COVID-19 (continued). "Circulating leukocyte count, IL-6, and myeloperoxidase levels were positively correlated with MMP-9 concentration in patients with COVID-19, which suggests that MMP-9 is associated with inflammation in patients with COVID-19." (PMID 36142454, 2022). "In addition, IL-6, which is one of the cytokines most expressed in the COVID-19 patient, is a multi-effective cytokine with both anti-inflammatory and pro-inflammatory roles." (PMID 36499222, 2022). "Therefore, administration of an IL-6 inhibitor has been established as a therapeutic strategy for COVID-19." (PMID 36282812, 2022). "Furthermore, COVID-19 patients with neurological symptoms show altered inflammatory mediators such as IL-6 and TGF-β in both serum and CSF when compared to patients with only mild symptoms." (PMID 35982454, 2022). "On the other hand, the fact that we conducted basic experiments using an IL-6 dose/concentration significantly higher than that found in patients with COVID-19 could represent a limitation." (PMID 35665254, 2022). "Baricitinib, specifically, is an orally administered inhibitor of JAK1 and JAK2 that blocks the intracellular signaling pathways of cytokines, which are known to be elevated in severe COVID-19, including IL-2, IL-6, interferon-γ and granulocyte-macrophage colony-stimulating factor." (PMID 36304162, 2022). "The genes, including IL6, IL1B, and TNF, encode inflammatory cytokines of CRS in COVID-19." (PMID 35979235, 2022). "It is further suggested that IL-10 may be a better marker of the disease conditions because its levels are elevated earlier than IL-6 in patients with COVID-19." (PMID 36233111, 2022). "This could suggest the potential use of IL-6 salivary level as a non-invasive biomarker predicting COVID-19 severity." (PMID 36163397, 2022). "IL-6 was found to suppress T lymphocyte activation, that could contribute to lymphopenia in COVID-19 patients." (PMID 35529862, 2022). "IL-6 might be a reliable indicator for the COVID-19 severity, and a higher level of IL-6 concentration was found in severe COVID-19 patients than in the moderate or mild groups." (PMID 36699595, 2022). "It is broadly accepted that a prolonged state of low-grade neuroinflammation mediated by elevated IL-1Beta and IL-6, along with central mechanisms represented by hypothalamic involvement and altered serotoninergic level, would eventually lead to post-COVID-19 fatigue." (PMID 35962348, 2022). "Contradictorily, another correspondence suggested ibuprofen might prevent COVID-19 fatalities by reducing cytokine release syndrome found in severely ill COVID-19 patients by reducing interleukin-6 levels." (PMID 35511939, 2022). "IL-17 is a promising target in COVID-19, since it operates upstream of both, IL-1 and IL-6." (PMID 35213582, 2022). "A few of these molecules have been translated to COVID-19 treatment, as for instance anti IL-6 monoclonal antibodies, anti-JAK1/2 small molecule inhibitors, both approved by national and international drug regulatory agencies for treating autoimmune conditions such as rheumatoid arthritis." (PMID 36289890, 2022). "We have previously expressed skepticism for rationale to use IL-6 inhibition to treat COVID-19." (PMID 35814227, 2022). "A quarter of the patients with progression to COVID-19-associated ARDS presented with macrophage activation syndrome: high levels of CRP, ferritin, d-dimer, AST/ALT, tumor necrosis factor (TNF)-alpha, interleukin (IL)-1beta and IL-6." (PMID 36289881, 2022). "Indeed, hyperglycemia has been suggested to increase the expression of cytokines, including IL-6 and tumor necrosis alpha (TNFα), in patients with severe COVID-19." (PMID 35329890, 2022). "Our findings support observations that increased IL-6 levels in patients with COVID-19 may be a predictor of progression of COVID-19 infection." (PMID 35572676, 2022). "First, IL-6 may serve as an early biomarker to monitor inflammatory and immune responses in COVID-19 patients." (PMID 35248063, 2022).
COVID-19 (continued). "To assess the general landscape of immune perturbation in different clinical settings of COVID-19, we contemporary measured the concentration in peripheral blood of six cytokines involved in the inflammation orchestrating: IL-6, IL-1β, IL-17A, TGF-β, TNF-α and IFN-γ." (PMID 35508575, 2022). "As in Case 5, in which the use of an anti-IL-6 agent was indicated, immunomodulation with biological agents has been used and seems to play an important role in adult patients with severe COVID-19, to whom the use of Tocilizumab was described for pharmacological inhibition of this interleukin." (PMID 35442269, 2022). "A recent series of cytokine-focused prospective studies in critically ill COVID-19 patients found that IL-6 concentrations were significantly higher than previously reported using clinical IL-6 measurements, both in absolute terms and relative to other inflammatory airway conditions like ARDS." (PMID 36452899, 2022). "Interleukin 6 (IL-6) concentrations and the severity of the COVID-19 patients." (PMID 35242747, 2022). "Unfortunately, we were unable to obtain biochemical measures of inflammation (C-reactive protein and interleukin-6) and other markers (fibroblast growth factor 23 and prealbumin) in the majority of study participants at all time-points due to the COVID-19 pandemic." (PMID 35810296, 2022). "The number of T lymphocyte subsets, including naïve T4/T8 cells, central memory T4/T8 cells, PD1+ depletes T8 cells, and effector memory T8 cells, was moderately increased in COVID-19 patients with normal IL-6 levels, and with increasing IL-6 levels, these lymphocyte subset counts declined." (PMID 36403042, 2022). "In this report we have demonstrated that IL-6 increases soluble levels of adhesion molecules suggesting that this might be one of the chemical mediators modulating the observed COVID-19 endothelial effects." (PMID 35050236, 2022). "COVID-19 activates CD4+ T cells to differentiate into pathogenic Th1 cells, which release GM-CSF and other proinflammatory cytokines that further activate monocytes to release IL-6." (PMID 35062368, 2022). "Molecular mimicry of SARS-CoV-2 and acetylcholine receptor and cytokine storm due to TNF-α, IFN-γ, IL-6, regulatory T cell (Th-17), and IL-17 is contributed to the ARDS in COVID-19 and myasthenic crisis and also associated with the severity, poor outcome, and the mortality." (PMID 35818475, 2022). "For instance, aberrant IL-6/JAK/STAT-3 signaling potentiates inflammatory responses in COVID-19, therefore aggravating disease severity; in the context of cancer, it attenuates anti-tumor T-cell mediated responses and favors tumor growth, survival, invasiveness, and or/metastasis." (PMID 36298472, 2022). "To demonstrate this, we have proven that TXA2 is statistically higher in moderate COVID-19 patients at hospital admission compared to severe COVID-19 patients, and IL-6 is higher in severe COVID-19 patients at hospital admission compared to moderate COVID-19 patients." (PMID 36298501, 2022). "Additionally, other groups have shown, through various techniques, the tremendous impact COVID-19 has on leukocytes and platelets in particular, including IL-6-mediated platelet activation and STAT3 phosphorylation within monocytes and T cells." (PMID 35681519, 2022). "Besides, an Egyptian study observed a decreased in IL-6 and IL-1 cytokines in COVID-19 patients treated with IVM, with a reduction in the mortality rate and the hospitalization time." (PMID 35889004, 2022). "Interleukin-6 (IL-6) has become one of the biomarkers used to detect the severity of COVID-19." (PMID 35884289, 2022). "Among them, all the death patients with COVID-19 had higher IL-6 levels than the survive patients." (PMID 35237162, 2022). "The authors thus suggested that both miRNAs, along with enhanced lncRNA levels, may promote IL-6R/CCL2 translation in COVID-19 patients, contributing to IL-6-induced cytokine storms." (PMID 35207576, 2022).
COVID-19 (continued). "Furthermore, in light of the importance of IL-6 detection with infectious diseases such as COVID-19, the here presented liposome-based LFA indicates that liposomes will rival the prevalence of colloidal gold as a benchmark in LFA analysis." (PMID 34773470, 2022). "As interleukin-6 (IL-6) is a critical cytokine in CS-induced mortality in patients receiving engineered T cell therapy, it was first suggested as a potential therapeutic target for COVID-19 CS." (PMID 35529862, 2022). "In addition, we demonstrated that cells infected with SARS-CoV-2 exhibit high expression of IL-1β and IL-6, both components of the SASP and implicated in systemic features of severe COVID-19." (PMID 35086840, 2022). "Growing evidence suggest that severe COVID-19 patients have higher plasma levels of cytokines, such as IL-1β, IL-6, and IL-10, and concentration of these cytokines in the plasma may differentiate mild, moderate, and severe cases." (PMID 36422492, 2022). "COVID-19 respiratory distress begins with an early inflammation so that pulmonary compliance is reduced by activation of intercellular inflammatory pathways, cytokine synthesis, or storm (excessive release of IL-2, IL-6, IL-7, IL-8, IL10, and TNF-α)." (PMID 35656183, 2022). "The lipoprotein dyslipidemia associated with COVID-19 severity (high TG and low total, LDL and HDL cholesterol) was inversely correlated with inflammatory biomarkers such as increased levels of serum CRP, IL-6, IL-8, and IL-10." (PMID 35956081, 2022). "Furthermore, imbalanced and inappropriate inflammatory response, which is defined by low levels of type I and III IFNs contrasted to elevated chemokines and high expression of IL-6, drives the development of severe COVID-19." (PMID 35287350, 2022). "IL-6 has been linked to CRS severity in multiple studies and surpassed 50 pg ml−1 (research grade measurement) in eight patients (22.2%), levels frequently observed in patients with severe COVID-19 or CAR-T-cell-induced CRS17–19." (PMID 35715501, 2022). "Several clinical or biological markers, including ferritin, C-reactive protein, and pro-inflammatory interleukin-1 and interleukin-6, have currently been identified to help predict the course of COVID-19 and, therefore, can potentially help to guide IGAM usage." (PMID 35799196, 2022). "Also, it was observed that patients suffering from severe COVID-19 exhibited a larger IL-6/IFN-γ ratio than moderate cases." (PMID 35782361, 2022). "Targeting the appropriate cytokine is one of the main objectives of current studies, and one of the first approaches to COVID-19 cytokine storm syndrome treatment was targeting the IL-6, since early during the pandemic, IL-6 concentrations were noted to be elevated." (PMID 35336980, 2022). "Finally, broad anti-inflammatory treatment was associated with a reduction in CRP, IL-6 levels as well as length of ICU stay and ventilation-days in critically ill COVID-19 patients." (PMID 35007290, 2022). "IL-6 and TNF-α may be the most critical factors causing CS; IL-6 and IL-10 levels can be used as a primary index for predicting COVID-19 outcomes." (PMID 36278166, 2022). "In our study, elevated levels of IL-6, IL-10, and CCL5 seemed to be remarkable biomarkers for differentiating patients with severe COVID-19 from AS and NI patients, suggesting an association with progression to severe COVID-19." (PMID 36287506, 2022). "The use of interleukin 6 inhibitors like tocilizumab for treating patients with severe COVID-19 is also associated with increased risk, though none of our patients in the study had received it." (PMID 35155019, 2022). "With a limited number of antiviral therapies against COVID-19, future studies need to investigate whether antagonists of IL-6 and its receptor significantly improve the clinical outcomes of COVID-19." (PMID 35248063, 2022). "Finally, the high peripheral levels of IL-6 and IL-10 have been highlighted as a predictor of COVID-19 severity." (PMID 36685603, 2022).
COVID-19 (continued). "Patients suffering from severe COVID-19-induced acute respiratory distress syndrome have been described to display elevated levels of Interleukin-6 (IL-6), lymphopenia with low counts of CD8+ T cells, natural killer (NK) and naïve T helper cells, while B cells remained mainly unaffected." (PMID 35619701, 2022). "Specifically, non-COVID-19 patients had higher IL-6 levels (36.6 pg/mL vs. 16.1 pg/mL, p = 0.01)." (PMID 35207659, 2022). "Specifically, tocilizumab, an anti-IL-6 receptor monoclonal antibody, has been found to be effective in regulating the levels of cytokines such as IL-6 and IL-17 and its administration in COVID-19 patients has been shown to reduce the lethality rate at 30 days." (PMID 35444637, 2022). "In addition to being a therapeutic target, raised IL-6 levels predict development of an oxygen requirement and, along with an elevated NLR, form part of the COVID-19-associated hyperinflammatory syndrome (cHIS) diagnostic criteria." (PMID 35323932, 2022). "Nevertheless, the use of IL-6 or CRP as prognostic markers seems inconsistent during COVID-19." (PMID 35956186, 2022). "Therefore, although promising, these two mediators should be considered carefully as targets for COVID-19 therapy with anti-IL-6 and anti-TNF monoclonal antibodies." (PMID 35720401, 2022). "This assumption is confirmed by the fact that a significant increase of the amount of bacterial lipopolysaccharide (LPS), and soluble sCD14 receptor associated with elevated systemic levels of IL-6, TNF-α, CCL5/RANTES and CCL2/MCP-1 was observed in critically ill patients with COVID-19." (PMID 36325402, 2022). "While initially, the results of treatment with biological anti-cytokines (in uncontrolled case series of anti-IL-6 and anti-IL-1 biologics) in COVID-19 were encouraging, current, increasingly documented studies have shown more intricate pathogenic mechanisms and heterogeneous results." (PMID 35457086, 2022). "High levels of IL-6 are often found in the blood of patients infected with COVID-19." (PMID 35722585, 2022). "Tocilizumab, a kind of antibody that targeted the IL-6 signaling pathway, was demonstrated to be effective in treating severe COVID-19 patients, and biomarkers including C-reactive protein, procalcitonin, D-dimer, and lymphocyte levels were decreased after receiving tocilizumab administration." (PMID 35540724, 2022). "For an instant, IL-6, which is one of the proinflammatory molecules in the state of inflammaging in elderly individuals, is also highly correlated with mortality rate among COVID-19 patients." (PMID 36369012, 2022). "Considering these points, the question arises regarding whether anti-IL-6 agents may have a detrimental impact on patients with COVID-19." (PMID 35619180, 2022). "Administration of anti-IL-6, Tocilizumab, Sarilumab, and glucocorticosteroids could improve the evolution of critically ill patients with COVID-19 but are unable to prevent the occurrence of pulmonary fibrosis." (PMID 36010377, 2022). "Therefore, when IL-6 cannot be examined, the mNUTRIC score can be considered safe and effective for the prediction of mortality in COVID-19 patients." (PMID 35685514, 2022). "Orosomucoid is known to be regulated by TNF-β, IL1β, IL6 and IL6-related cytokines, along with immunomodulating effects like inhibiting neutrophil migration, and has been employed as a biomarker in COVID-19." (PMID 35438176, 2022). "Higher IL6 levels are commonly found in the three common comorbidities, which may lead to severe COVID-19." (PMID 35165525, 2022). "Alterations to NK cells in stroke and COVID-19 patients may be due to the high concentrations of IL-6 in the circulation, as NK cell numbers inversely correlate with IL-6 concentration and IL-6 has been shown to impair NK cell cytolytic functions in vitro." (PMID 38566903, 2022).
COVID-19 (continued). "Indicative cytokines in severely ill COVID-19 patients are characterized by boosted expression of IL-6, TNF-α, IL-17 macrophage inflammatory proteins 1-α (MIP-1α), MCP3, GM-CSF, IL-2, and IP-10, in addition to the elevated chemokines (IP-10, CCL2/MCP1, CXCL1, CXCL5)." (PMID 36081516, 2022). "Elevated levels of IL6 and TNFα are also reported in severe COVID-19 cases." (PMID 35631059, 2022). "IL-6 and JAK/STAT signaling pathways are strongly associated with the COVID-19 CS." (PMID 35562935, 2022). "In COVID-19, IL-6 is believed to drive multi-organ injury, the most severe form of the illness." (PMID 36380355, 2022). "In addition to IL-6, the inflammatory phase of COVID-19 is potentially exacerbated under the influence of another distinguished pro-inflammatory cytokine, IL-17." (PMID 35021853, 2022). "Both IL-6 and IL-8 increase in both serum and cord blood taken from patients with COVID-19." (PMID 35408809, 2022). "Thus, correlations were performed in the current investigation, implying that plasma levels of CRP, SAA, IL-6, CXCL10, VCAM-1, and IL-10, among the linked, exhibit a significant and beneficial association with COVID-19 patient progression." (PMID 35958594, 2022). "Similarly, other researchers had reported that hyperglycemic patients had greater levels of IL-6 during hospitalization for COVID-19." (PMID 35530861, 2022). "We have also reaffirmed, although not causal, the predictive value of high D-Dimer and IL-6 levels in predicting the development of PE and mortality in COVID-19." (PMID 35308552, 2022). "Patients who died from COVID-19 stand out for their elevated levels of IL-6, IL-10, and CCL2/MCP-1." (PMID 35336861, 2022). "In the severe form of COVID-19, the concentrations of IL-2, IL-6, IL-10, and IFN-γ were elevated." (PMID 35782361, 2022). "Based upon this evidence, therapeutic blockade of IL-6 signaling may constitute an efficient strategy to prevent respiratory function deterioration during COVID-19, reducing overall mortality in these subjects." (PMID 35645219, 2022). "Furthermore, IL-1β mediates Il-6 synthesis, a key proinflammatory cytokine in COVID-19 cytokine storm and a potent inducer of CRP." (PMID 36422492, 2022). "On the other hand, ROC analysis for the same four variables in the severe group of COVID-19 patients revealed that AUC were 0.844, 0.657, 0.765, 0.694 for IL-6, TXA2, NF-κB p50 and NF-κB p65 with sensitivities 100, 92, 74, and 70% and specificities of 68, 53, 74, and 60 %, respectively." (PMID 36298501, 2022). "Furthermore, median levels of CRP, GDF-15, IL-6, and sFlt-1 increased with COVID-19 disease severity, whereas the median level of sACE2 decreased with COVID-19 disease severity." (PMID 35453934, 2022). "Dysregulated innate immune responses occur in COVID-19 involving a central role for IL-6." (PMID 35531376, 2022). "Janus kinase (JAK) inhibitors (baricitinib, tofacitinib, imatinib) showed promising results for reducing mortality and intubation rates and have been approved in many countries for the treatment of the same population of COVID-19 patients as for IL-6 and IL-1 antagonists." (PMID 35214651, 2022). "A recent study also indicated that the overexpressed hsa_circ_0000479 in COVID-19 patients may regulate the expression of IL-6 and RIG-I by sponging hsa-miR-149-5p." (PMID 36439162, 2022). "Interleukin-6 (IL-6) levels have been reported to be greater in both COVID-19 and DKA, suggesting that this may be a key prognostic factor." (PMID 36465737, 2022). "While IL-15 and IL-16 are clustered with neutrophil-derived cfDNA in SOTRs with COVID-19, inflammatory cytokines such as IL-15, IL-6, IL-16, and MIP-1α are clustered with total (ncfDNA) and tissue-specific cfDNA from adipocytes, monocytes, erythroblasts, and neutrophils in Non-SOT COVID-19 patients." (PMID 35075453, 2022).